IL13 (interleukin 13)
Diseases named in the same sentence as IL13 in open-access papers (continued):
Sharing a sentence is not in itself a finding about the gene and the disease.
systemic inflammatory response syndrome (3 papers, 2018 to 2025). SIRS is a serious condition related to systemic inflammation, organ dysfunction, and organ failure. "Paradoxically, these same patients showed hypomethylation of the IL-10 gene, suggesting concurrent activation of anti-inflammatory pathways (TGF-β, IL-10, IL-13) as part of the CARS that follows systemic inflammatory response syndrome (SIRS)." (PMID 40868190, 2025). "Similarly, TNF-α soluble receptor levels were shown to raise in plasma of burn-induced systemic inflammatory response syndrome children whereas IL-13 serum levels remained unchanged." (PMID 29675435, 2018). "In systemic inflammatory response syndrome (SIRS), anti-inflammatory cytokines (IL-10, IL-4, IL-13, and PGE2) balance pro-inflammatory cytokines, a process known as the “cytokine storm”, leading to excessive inflammation." (PMID 39337069, 2024).
ulcer (3 papers, 2014 to 2023). "On the other hand, IL-13 expression was higher in the vicinity of the ulcer than in the morphological-preserving area, suggesting that IL-13 may contribute to ulcer formation from inflammation." (PMID 37834420, 2023). "L. major-infected BALB/c mice display a persistent Th2 response with high levels of IL-4 and IL-13 in contrast to C57BL/6 mice and develop ulcerative skin lesions." (PMID 37908348, 2023). "IL-13 expression was significantly increased in the near ulcer rather than in the ulcer, and constant expression was confirmed in the morphology-preserving part." (PMID 37834420, 2023). "The reason why we could not detect an increase in IL-13 expression in the ulcer area was thought to be that the ulcer area is extremely cytotoxic, resulting in high levels of damage to nucleic acids." (PMID 37834420, 2023).
visceral leishmaniasis (3 papers, 2014 to 2023). A severe form of leishmaniasis characterized by irregular bouts of fever, substantial weight loss, swelling of the spleen and liver, and anemia (which may be serious). "Consequently, current research within our team is aimed at unraveling IL-4 and IL-13 signaling on specific target immune cells during visceral leishmaniasis using our cell-type-specific IL-4Rα-deficient mouse models." (PMID 29176972, 2017). "In visceral leishmaniasis both, IL-4 and IL-13 play a positive role in granuloma formation and maturation (also pointing to IL-4Rα-dependent inflammatory cell recruitment as found here for pulmonary cryptococcosis) and are essential for optimal development of IFN-γ responses." (PMID 24475277, 2014).
vitamin A deficiency (3 papers, 2012 to 2018). Deficiency of vitamin A due to malnutrition, malabsorption, or dietary lack. "Also, the data could suggest that the vitamin A deficiency seen in the positive responders may have resulted in the dendritic cells being altered toward being more inflammatory producing high levels of IL-13 and TNF-α thus creating a favorable environment in which ATRA has an effect." (PMID 29801999, 2018). "Vitamin A deficiency (control) significantly decreased the mRNA expression levels of MUC2, IgA, EGFR, IL-13 and TGF-β in trachea tissue." (PMID 26422233, 2015). "By quantitative real-time PCR analysis (qRT-PCR) of isolated liver lymphocytes, we found that vitamin A deficiency significantly reduced the expression of IL-4, IL-5, and IL-13 but not of IFNγ." (PMID 22927819, 2012).
abortion (2 papers, 2019 to 2024). the ending of pregnancy by removing a fetus or embryo before it can survive outside the uterus. "Surveys have shown that decreased IL-13 concentration in maternal body in early pregnancy could lead to embryo abortion." (PMID 31043168, 2019). "A study showed that IL-13 is a Th2-type cytokine, which can inhibit Th1 cells, reduce the maternal immune rejection of the fetus, activate B cells to produce large amounts of IgG and complete Th1 transformation into Th2; therefore, IL-13 plays an important role in preventing fetal abortion." (PMID 31043168, 2019).
Achalasia (2 papers, 2015 to 2021). A disorder of esophageal motility characterized by the inability of the lower esophageal sphincter to relax during swallowing and by inadequate or lacking peristalsis in the lower half of the body of the esophagus. "Type II achalasia patients showed an increase in IL-13-producing cells when compared with control tissue and types I and III achalasia patients." (PMID 26078981, 2015).
acute pancreatitis (2 papers, 2009 to 2026). An acute inflammatory process that leads to necrosis of the pancreatic parenchyma. "We evaluated the activation phenotype in peritoneal macrophages during the progression of an experimental model of acute pancreatitis induced in rats by intraductal administration of 5% sodium taurocholate and the effect of IL-4 and IL-13 to modulate this activation." (PMID 19646232, 2009). "Our results indicate that peritoneal macrophages adopt a pro-inflammatory activation early during acute pancreatitis and that they could be reprogrammed in vitro to a reparative M2 phenotype by IL-4 and IL-13." (PMID 19646232, 2009).
adenomyosis (2 papers, 2020 to 2022). The growth of endometrial tissue inside the muscular wall of the uterine corpus. "Therefore, STAT3, VIM, VEGFA and HSP90B1 that were also annotated in interleukin-4 and interleukin-13 signalling in the present GSEA need to be validated to verify potential downregulation of this pathway in women with adenomyosis." (PMID 32933042, 2020).
amyloid (2 papers, 2024 to 2025). "Previous research has linked IL-13 to a better prognosis in neurodegenerative disorders like AD by promoting macrophage uptake of beta-amyloid and reducing amyloid plaque formation in the CNS." (PMID 40362746, 2025). "Moreover, increased IL-10 and IL-13 were significantly associated with moderate to severe neurofibrillary tangle pathology in brain, but not amyloid plaques or Lewy bodies, indicating perhaps that IL-10 and IL-13 might contribute more to tau than amyloid pathology." (PMID 39071802, 2024).
Ascaris lumbricoides infection (2 papers, 2025). "We previously found that active Ascaris lumbricoides infection (ascariasis) is associated with decreased H3 and H4 histone acetylation at the promoter of the IL-13 encoding gene (IL13) poising its expression." (PMID 40943268, 2025).
atopic march (2 papers, 2023 to 2025). sequential manifestations of different allergic diseases such as eczema, asthma and rhinitis. "In particular, the T helpers 2 (Th2) subset, through its cytokine signatures made of interleukins (ILs), such as IL-4, IL-5, IL-10, and IL-13, as well as mast cells and their related histamine pathways, contribute greatly to the perpetuation and evolution of the atopic march." (PMID 36675006, 2023).
autoimmune myocarditis (2 papers, 2015 to 2017). Autoimmune myocarditis is an autoimmune disease that affects the heart. "The other mechanism by which chronic myocardial damage can occur is through the development of autoimmune myocarditis, and IL13 seems to offer protection against experimental autoimmune myocarditis by moderating macrophage differentiation." (PMID 28707261, 2017). "IL-13 prevented autoimmune diabetes in NOD mice, protected against experimental autoimmune myocarditis by regulating macrophage differentiation, prolonged allograft survival, and attenuated acute kidney allograft injury." (PMID 27095999, 2015).
Barrett esophagus (2 papers, 2020 to 2024). Esophageal lesion lined with columnar metaplastic epithelium which is flat or villiform. "In the so-called Barrett’s esophagus an acute inflammatory state (esophagitis) evolves towards a state of chronic inflammation characterized by presence of IL-4 and IL-13, suppressive M2 macrophages and MDSCs." (PMID 38638445, 2024).
bipolar disorder (2 papers, 2020 to 2021). A disorder of the brain that causes unusual shifts in mood, energy, activity levels and the ability to carry out day-to-day tasks. "However, there was weak evidence for a protective effect of IL-13 (IVW β=-0.12, SE=0.06, p=0.063) and of IL-17 (IVW β=-0.11, SE=0.06, p=0.070) on the risk of bipolar disorder." (PMID 34280516, 2021).
brain cancer (2 papers, 2020 to 2025). A primary or metastatic malignant neoplasm affecting the brain. "IL13RA2, a high-affinity receptor for IL13, is highly expressed in primary brain cancers, many extracranial solid tumors, and in lung- and brain-seeking metastatic variant cell lines." (PMID 40663259, 2025).
Burkitt lymphoma (2 papers, 2020 to 2021). A rare form of malignant mature B-cell non-Hodgkin lymphoma. "Furthermore, cocultures of NLRP11-expressing Burkitt's lymphoma cells and naïve human peripheral CD4+ T lymphocytes had reduced IFN-γ and IL-17A production, whereas IL-13 and IL-10 cytokines did not change." (PMID 32832566, 2020).
C. perfringens infection (2 papers, 2021 to 2023). "Fasina and Lillehoj reported that C. perfringens infection induced intestinal inflammation via the activation of Th2 and Th17 cells and inhibition of Treg cells, proven by the upregulation of IL-13 and IL-17 and downregulation of TGF-β4." (PMID 34136557, 2021). "Post- C. perfringens infection, there was a significant increase in intestinal IL-13 (p ≤ 0.001) and IL-18 (p ≤ 0.05) expression in both rL. lactis treated only and rL. lactis treated and subsequently C. perfringens infected chickens compared to control chickens." (PMID 38164397, 2023).
Cachexia (2 papers, 2024). Severe weight loss, wasting of muscle, loss of appetite, and general debility related to a chronic disease. "Logistic regression analysis showed that high saliva TGF-β and IL-13 levels were independent risk factors for cachexia." (PMID 39272892, 2024). "The diagnostic accuracy of IL-13 and TGF-β in the serum and saliva of patients with and without cachexia was determined by ROC curve analysis." (PMID 39272892, 2024).
candidiasis (2 papers, 2010 to 2020). Infection with the organism Candida. "The involvement of Dectin-1 in improving the resolution of candidiasis by PPARγ ligands is in line with our results which showed for the first time that the increase in Dectin-1 cell surface expression by IL-13 was mediated by the PPARγ signaling pathway." (PMID 20062524, 2010). "However, we found that gpi7 mutant vaccination could significantly increase the levels of TH2-type effector cytokines, such as IL-4 and IL-13, in the spleen and serum of mice when challenged by C. albicans SC5314, which suggests that these play a role in the immunoprotection against candidiasis." (PMID 32765468, 2020).
cataract (2 papers, 2020 to 2024). Partial or complete opacity of the crystalline lens of one or both eyes that decreases visual acuity and eventually results in blindness. "In the present study, IL-13 was significantly lower in the nAMD and PCV group than in the cataract group, while reports of aqueous humor IL-13 level in nAMD or PCV are still controversial according to recent reports." (PMID 31914968, 2020). "So, we focused in the present study on evaluation of selected pro-inflammatory cytokines (IL-1β, IL-6, IL-8, IL-17A, and TNF-α), anti-inflammatory cytokines (IL-4, IL-10, and IL-13), and the IL-1 receptor antagonist (IL-1Ra) in the aqueous humor of FECD and/or cataract eyes." (PMID 38792359, 2024).
Chlamydia infection (2 papers, 2011 to 2021). "Anyway, targeted blocking of IL-13 action in Chlamydia infection through clarification of cell specific IL-13 mechanisms is a critical goal to aim for in related research." (PMID 34093528, 2021). "Therefore, it is hypothesized that IL-13 mediates Chlamydia-related immunopathology and reflects disease severity after Chlamydia infection." (PMID 34093528, 2021).
chronic hepatitis B (2 papers, 2024 to 2026). "Concentrations of IL-13 in the plasma were independently associated with increased CAP score in chronic hepatitis B patients, with every increase of 1 unit of IL-13 being associated with a 0.98 unit increase in CAP score." (PMID 39200991, 2024).
chronic pancreatitis (2 papers, 2017 to 2026). A chronic inflammatory process causing damage and fibrosis of the pancreatic parenchyma. "Our study demonstrates that the IL-4/IL-13 STAT6-signaling pathway represents a critical regulatory mechanism suppressing the inflammation and stimulating wound healing and organ regeneration during acute and chronic pancreatitis." (PMID 41486955, 2026).
Cognitive decline (2 papers, 2016 to 2021). "Cognitive decline in episodic, semantic, and working memory was associated with higher IL-1α, IL-13, and MDC levels in the temporal cortex, respectively." (PMID 34218796, 2021). "In the control group, there were bivariate correlations between IL‐1β, IL‐6, and IL‐8 and lower MMSE scores and between IL‐13 and slower rate of cognitive decline (albeit at a significance level of P < 0.05 and notwithstanding correction for multiple testing)." (PMID 26999434, 2016).
degenerative disc disease (2 papers, 2014 to 2022). "A series of studies have shown that intervertebral disc degeneration can be alleviated by inhibiting IL-13, as well as blocking the associated cellular signaling pathways and inhibiting fibrosis in tissues." (PMID 35937989, 2022).
dengue haemorrhagic fever (2 papers, 2015 to 2018). "The increase in plasma expression of Th2 cytokines (i.e., IL-4, IL-13) may be associated with augmentation of vascular permeability and vascular leakage as seen in dengue haemorrhagic fever." (PMID 26271921, 2015).
dental caries (2 papers, 2021 to 2025). The decay of a tooth, in which it becomes softened, discolored, and/or porous. "We suggest a further validation of the four biomarkers (IL-4, IL-13, IL-2-RA, and eotaxin/CCL11) in the context of JAK/STAT signaling and dental caries." (PMID 33806927, 2021). "The current research identified four biomarkers (IL-4, IL-13, IL-2-RA, and eotaxin/CCL11) that enabled the correct diagnosis of dental caries in 37 out of 38 patients using RF analysis." (PMID 33806927, 2021).
diffuse midline glioma (2 papers, 2021 to 2024). A diffuse glioma that arises from the midline structures of the central nervous system. "A recent phase I trial of convection-enhanced delivery of an IL13-targeted exotoxin for H3K27-mutant diffuse midline glioma used the 43-item Impact of Pediatric Illness (IPI) Parent Report Form to record health-related QOL in five pediatric patients." (PMID 34771443, 2021).
dysplasia (2 papers, 2023 to 2025). A usually neoplastic transformation of the cell, associated with altered architectural tissue patterns. "However, our inverse associations with dysplasia are consistent with a previous study that found that IL‐2, IL‐5, IL‐8, IL‐10, IL‐13 and TNF‐alpha tend to be downregulated in low‐grade/moderate dysplasia of the pancreas compared to serous cystadenoma without dysplasia." (PMID 39482824, 2025). "Four of the 12 analyzed cytokines demonstrated elevated expression above control levels in all of the dysplasia cohorts (IL‐12, IL‐13, IP‐10, RANTES) and 2 demonstrated expression below control levels across all dysplasia cohorts (MCP‐1, MIP‐1β)." (PMID 38130766, 2023). "IL‐12, IL‐13, IP‐10, and RANTES expression was higher in all dysplasia cohorts as compared to controls." (PMID 38130766, 2023).
enteritis (2 papers, 2021 to 2022). Inflammation of the small intestine. "Therefore, blocking the IL-13 signaling pathway could also reduce the aggravation of enteritis caused by DEX." (PMID 36032134, 2022). "In addition, we investigated the change in the proportion of Th2 cytokines in the intestinal mucosa of mice with DSS‐induced enteritis using ELISA, finding that the mice with DSS‐induced enteritis displayed significantly higher IL‐4, IL‐5 and IL‐13 levels than the control group." (PMID 33569850, 2021).
exanthema (2 papers, 2023 to 2024). "Based on the significantly higher incidence of skin rashes occurring with MIS-C and the higher levels of cytokines (IL-5, IL-8, IL-13, and IL-33) known to influence eosinophil activity, we performed a further evaluation of eosinophils and ELR." (PMID 38932242, 2024).
fetal growth restriction (2 papers, 2023 to 2026). A fetus that does not grow beyond the 10th percentile of conventionally accepted weight for gestational age. "Fetal growth restriction (FGR) maternal IL-13 levels are lower than those in normal pregnancies." (PMID 38035087, 2023).
filariasis (2 papers, 2020 to 2021). "In the context of filariasis, IL-4 and IL-13 have been described as critical cytokines required for the expansion of tissue-resident macrophages that optimally maintain eosinophilic influx and effector responses at the site of infection." (PMID 32571840, 2020).
Gastric Metaplasia (2 papers, 2023 to 2024). Intestinal metaplasia of the gastric mucosa is an intermediate precancerous gastric lesion in the gastric cancer cascade from chronic gastritis and atrophy to dysplasia and adenocarcinoma. "In addition, IL13 production has been linked to mast cells, B cells, T cells, and macrophages during genetically induced gastric metaplasia, with inhibition of IL13 reducing metaplasia development." (PMID 37898600, 2023). "Due to the established link between IL25 and IL13, as well as the functional requirement we established for tuft cells and ILC2s during gastric metaplasia and tumor growth, we next investigated the extent by which these cytokines promote epithelial growth." (PMID 37898600, 2023).
gastritis (2 papers, 2024). Inflammation of the stomach. "Although the levels of IL-5, IL-6, IL-9, IL-10, IL-13, and IL-21 were higher in patients with gastritis than Hp- group, this increase was not significant." (PMID 39807418, 2024). "Indeed, IL4Rα-deficient mice develop gastritis, with immune cell infiltration and protein production resembling that found in wild-type controls but with no progression to SPEM, revealing the importance of IL-13 signaling during gastric carcinogenesis." (PMID 38339273, 2024).
gastrointestinal infection (2 papers, 2020 to 2022). "There is a report on the regulatory role of IL-31 interacting with its receptor in the intestine, after gastrointestinal infection by a parasite (Trichuris muris), which triggers a Th2 response and the production of IL-4 and IL-13." (PMID 35742951, 2022). "These mice also displayed increased pulmonary mucin production due to iILC2-derived IL-13, indicating that an intestinal infection alone can mobilize iILC2s to the lung and drive mucosal immunity at distal sites." (PMID 32793230, 2020). "Tuft cells act as early sentinels of intestinal infection by recognizing metabolites generated by pathogens that breech the mucosal barrier and produce substantially more IL-25 leading to increased ILC2-derived IL-13." (PMID 32793230, 2020).
Giardia infection (2 papers, 2017 to 2018). "Rather, prior Giardia infection resulted ingreater IL-4 and IL-13 and increased IL-9, a potential marker of mast cell activity." (PMID 28750066, 2017). "Untreated Giardia-infection may regulate innate and adaptive immune responses mediated by Th17 CD4+T cells and induction of Th1, Th2 and Th17 cytokines, including IL-2, IL-5, IL-6, IL-8, IL-12, IL-13, IL-23, IFN-γ and TNF-α." (PMID 30412580, 2018).
gout (2 papers, 2019 to 2020). A condition characterized by painful swelling of the joints, which is caused by deposition of urate crystals. "Nonetheless, we found higher plasma levels of IL-1β, IL-1ra, IL-4, IL-6, IL-8, IL-9, IL-13, IL-17, FGF-basic, IFNγ, and TNFα in acute gouty arthritis patients." (PMID 31739430, 2019). "Compared with WT mice, St2-/- mice showed significantly reduced expression of IL-1β, IL-6, IL-13, CCL11, G-CSF, CXCL1, CCL2 and CCL3 proteins in ankle tissues, suggesting St2-/- mice showed generally attenuated inflammatory response during gout." (PMID 33204337, 2020).
hand eczema (2 papers, 2021 to 2023). A form of contact dermatitis characterised by inflammation, redness and itching of the hands. "Two major classes of drugs emerging for the treatment of hand eczema include IL-4/IL-13 inhibitors and JAK inhibitors." (PMID 37496489, 2023).